COX19 (cytochrome c oxidase assembly factor COX19)
Description:
Assembly factor for cytochrome c oxidase (respiratory chain complex IV, CIV). Acts as a COX11 chaperone that supports COX11 copper coordination. Also stimulates SCO2-mediated metalation of COX2. Required for the transduction of an SCO1-dependent redox signal from the mitochondrion to ATP7A to regulate cellular copper homeostasis. In the absence of COX11, capable of stimulating copper delivery to the copper B site of COX1.
Synonyms: MGC104475
Tractability: PROTAC: ubiquitination databases record sites on it; its protein half-life has been measured.
Gene: Protein-coding gene on chromosome 7 (898,778 to 975,549, reverse strand). Ensembl gene ENSG00000240230.
Subcellular location: Cytoplasm, cytosol; Mitochondrion intermembrane space; Mitochondrion
Subcellular location (Human Protein Atlas): Cytosol
Pathways (Reactome):
Metabolism: Complex IV assembly
Protein localization: Mitochondrial protein import
Gene Ontology:
Molecular function: protein binding; protein folding chaperone
Biological process: intracellular copper ion homeostasis; mitochondrial respiratory chain complex IV assembly; protein maturation; protein folding
Cellular component: cytosol; mitochondrial intermembrane space; mitochondrion
Genetic constraint (gnomAD): Loss-of-function variants: 7 observed, 5.15 expected, observed/expected ratio (o/e) 1.36, 90% interval 0.74 to 1.91. That is too few expected variants to judge how well the gene tolerates losing a copy. Missense variants: 92 observed, 64.25 expected, observed/expected ratio (o/e) 1.43, 90% interval 1.21 to 1.7. Synonymous variants: 33 observed, 24.28 expected, observed/expected ratio (o/e) 1.36, 90% interval 1.03 to 1.79.
Homologues: Orthologues: chimpanzee COX19 (99% identical), guinea pig COX19 (86% identical), pig COX19 (86% identical), mouse Cox19 (81% identical), zebrafish cox19 (72% identical), Caenorhabditis elegans cox-19 (40% identical), Drosophila melanogaster CG42496 (39% identical). Paralogues in human: CHCHD5 (17% identical).
Diseases named in the same sentence as COX19 in open-access papers:
COX19 is named in the same sentence as 8 diseases in open-access papers, as found by Europe PMC text mining. Sharing a sentence is not in itself a finding about the gene and the disease. The quoted sentences say what the papers report.
cervical cancer (1 paper, 2016). A primary or metastatic malignant neoplasm involving the cervix. "Although Gal-7 affects the specific cervical cancer networks in different ways, we identified a group of eight molecules that are regulated in both cell lines: CRYAB, TACSTD2, BCL-3, COX19, OASL, CDKN2A/p14ARF, NIBAN/FAM129A, and FST." (PMID 27558259, 2016).
colorectal cancer (1 paper, 2025). A primary or metastatic malignant neoplasm that affects the colon or rectum. "COX19, a target gene of MACC1, regulates mitochondrial activity and drives tumour progression in colorectal cancer." (PMID 40391581, 2025).
glioblastoma (1 paper, 2021). The most malignant astrocytic tumor (WHO grade IV). "For other activities, puerarin downregulated cytochrome c oxidase 19 (Cox19), fat storage-inducing transmembrane protein 2 (Fitm2), and glioblastoma amplified sequence (Gbas)." (PMID 34707778, 2021).
glioma (1 paper, 2023). A benign or malignant brain and spinal cord tumor that arises from glial cells (astrocytes, oligodendrocytes, ependymal cells). "Cytochrome c oxidase assembly factor 19(COX19) was involved in SCO1-dependent signaling essential for copper homeostasis, which was thought to be a risk factor in both gliomas and low-grade gliomas." (PMID 36882769, 2023).
cancer (3 papers, 2021 to 2022). A tumor composed of atypical neoplastic, often pleomorphic cells that invade other tissues. "We therefore performed a LASSO-COX regression based on TCGA-COAD data and identified COX4I2 as well as COX19 in respiratory chain complexes as potential cancer risk factors." (PMID 36064310, 2022).
tumor (3 papers, 2022 to 2025). "Given the crucial role of ROS in the tumour microenvironment and its potential impact on tumour immunotherapy, further research on the relationship between COX19 and immune cells is warranted." (PMID 40391581, 2025). "COX19 has been confirmed to be a key factor in the inhibition of tumor cell apoptosis by microRNA-21, and inhibition of COX19 expression may enhance apoptosis and reduce tumor cell proliferation." (PMID 36497289, 2022). "The data extracted from GSE37182 and GSE10950 indicated that there was a significant difference between COX19 and COX4I2 expression in tumor tissues and controls (P < 0.05)." (PMID 36064310, 2022).
COX19 also shares sentences with these, for which no sentence is quoted: encephalomyopathies (1 paper); osteoporosis (1).